ALKBH7 (alkB homolog 7, RNA demethylase)
Diseases named in the same sentence as ALKBH7 in open-access papers (continued):
Sharing a sentence is not in itself a finding about the gene and the disease.
cancer (9 papers, 2017 to 2025). A tumor composed of atypical neoplastic, often pleomorphic cells that invade other tissues. "TMB and MSI can be sensitive predictors of immune checkpoint inhibitor efficacy, and ALKBH7 expression was associated with TMB in 7 cancer types and MSI in 12 cancer types." (PMID 39400540, 2024). "ALKBH7 expression was significantly different in different immune subtypes and molecular subtypes in many cancer types, suggesting that ALKBH7 is a promising diagnostic pan-cancer biomarker and participates in immune regulation." (PMID 35222541, 2022). "In the present study, immunotherapy biomarkers (TMB and MSI) and the tumor stemness index showed significant associations with ALKBH7 in some cancers." (PMID 35222541, 2022). "The association between ALKBH7 expression and patient prognosis was estimated in the pan-cancer dataset." (PMID 35222541, 2022). "Experimental spectroscopy studies with purified proteins validate our MD predictions and corroborate the conclusion that this cancer-associated mutation affects productive cosubstrate binding in ALKBH7." (PMID 28231280, 2017). "Firstly, we observed the association between ALKBH7 expression and the immune genes, including immunomodulator genes and immune checkpoint-related genes, which played essential roles in tumor immunotherapy for cancers." (PMID 39400540, 2024). "ALKBH7 was associated with the TMB in 7 cancers and MSI in 13 cancers." (PMID 35222541, 2022). "By analyzing well-recognized immune signatures, we further explored the relationship between ALKBH7 expression and immune cell infiltration across pan-cancer." (PMID 39400540, 2024). "By performing RNA m1A, m5C, and m6A methylation and DNA methylation analysis, we found that ALKBH7 was negatively correlated with RNA modification-related genes and DNA methylation in most cancers, and the exact mechanism needs further investigation." (PMID 39400540, 2024). "To find out the correlation between ALKBH7 expression and drug sensitivity in pan-cancer, we collected IC50 data from Cell Miner and GDSC databases." (PMID 39400540, 2024). "Another important finding is that ALKBH7 expression is highly correlated with immune infiltration of cancer and that ALKBH7 expression is significantly correlated with NK cells, pDCs, CD8+ T cells, neutrophils, central memory T cells, and γδ T cells." (PMID 39400540, 2024). "Although previous analysis for has confirmed the prognostic value of ALKBH7 in some cancers, we performed a more detailed and comprehensive bioinformatics analysis to determine its impact on multiple cancer types, especially on HNSC." (PMID 39400540, 2024). "The findings showed that ALKBH7 mRNA expression was down-regulated in seven cancer types (COAD, HNSC, KIRC, LUAD, STAD, THCA, and UCEC) and up-regulated in only four tumors (BRCA, KICH, LIHC, and PRAD), in consistent with a previous study." (PMID 39400540, 2024). "We found that ALKBH7 was negatively correlated with most immune checkpoint-related genes in pan-cancer." (PMID 39400540, 2024). "We found that ALKBH7 was expressed differentially in pan-cancer, and correlated with a satisfied prognosis especially in HNSC." (PMID 39400540, 2024). "Our pan-cancer analysis revealed a significant reduction in ALKBH7 expression in various tumor tissues compared to normal tissues, especially in HNSC." (PMID 39400540, 2024). "The further analysis was conducted to supplementally show the expressions of ALKBH7 in different cancer cells and normal tissues according to the CCLE and the GTEx datasets." (PMID 39400540, 2024). "DNA and RNA modification occurred at a pervasive level along with the reduction of ALKBH7 expression in multiple types of cancers." (PMID 39400540, 2024).
cancer (continued). "Recent studies have identified the role of ALKBH7 in the progression of several cancers and its relationship to immune cell infiltration." (PMID 37654657, 2023). "A pan-cancer analysis showed that ALKBH7 expression correlated with the expression of immune checkpoint (ICP) genes in many cancers and was mainly negatively correlated." (PMID 37007161, 2023). "Bioinformatic analysis has shown that elevated ALKBH7 expression can be detected in most cancers compared to normal tissues, such as HCC, lung adenocarcinoma, and serous ovarian carcinoma." (PMID 37007161, 2023). "This information contributes to the understanding of the function of ALKBH7 in cancer development and its role in immunology." (PMID 35222541, 2022). "In this study, we observed high ALKBH7 expression in 17 cancers and low expression in 5 cancers compared to paired normal tissues." (PMID 35222541, 2022). "In the present study, we explored changes in the expression and prognostic value of ALKBH7 in 33 cancers." (PMID 35222541, 2022). "Next, ALKBH7 expression in different immune subtypes and molecular subtypes of human cancers was explored to determine its potential mechanism of action." (PMID 35222541, 2022). "Recent studies have identified a role for ALKBH7 in the occurrence and progression of cancer, and this protein is related to cellular immunity and immune cell infiltration." (PMID 35222541, 2022). "NK T cells and CD4+ Th1 T cells were positively correlated with ALKBH7 gene expression in most cancers." (PMID 35222541, 2022). "ALKBH7 expression displayed a strong relationship with dendritic cells in 8 cancer types, macrophages in 9 cancer types, neutrophils in 11 cancer types, CD8+ T cells in 14 cancer types, B cells in 8 cancer types and CD4+ T cells in 3 cancer types." (PMID 35222541, 2022). "Cox regression analysis of the DFI revealed that ALKBH7 expression significantly correlated with DFI in 4 types of cancer, including LUSC, OV, PAAD, and THCA." (PMID 35222541, 2022). "First, significantly higher ALKBH7 expression was detected in most cancers compared to paired normal tissues, consistent with previous studies." (PMID 35222541, 2022). "In this paper, a comprehensive pan-cancer study of ALKBH7 revealed the potential prognostic and immunotherapeutic value of ALKBH7 in human cancers." (PMID 35222541, 2022). "Considering the robust correlation between ALKBH7 expression and PAAD, PRAD and THCA, GSEA was performed to investigate the potential signalling pathways of ALKBH7 in these cancers." (PMID 35222541, 2022). "ALKBH7 expression affected DSS in six types of cancer, including BLCA, KIRP, LIHC, LUSC, PAAD, and PCPG." (PMID 35222541, 2022). "Next, ALKBH7 expression in immune and molecular subtypes of human cancer was explored using the TISIDB website." (PMID 35222541, 2022). "In contrast, significantly lower ALKBH7 expression was observed in a few human cancers (ESCA, HNSC, KIRC, LAML and TGCT)." (PMID 35222541, 2022). "In contrast, CD4+ Th2 T cells, memory CD4+ T cells, monocytes and mast cells were negatively correlated with ALKBH7 gene expression in most cancers." (PMID 35222541, 2022). "Univariate Cox regression analysis of the results from 33 types of cancer suggested that ALKBH7 expression significantly correlated with OS in 4 types of cancer, including BLCA, HNSC, KIRP, and PAAD." (PMID 35222541, 2022). "Together with our findings on ALKBH7, this suggests that AlkB family proteins influence tumor metabolism, immune escape, and therapy resistance, positioning them as promising therapeutic targets across cancer types." (PMID 41373809, 2025). "These complementary findings strengthen the hypothesis that ALKBH7 functions as a critical immunometabolic mediator, with structural features that may be exploited for therapeutic targeting of cancer." (PMID 41373809, 2025). "In this study, we analyzed the role of ALKBH7 in pan-cancer by using public multi-databases." (PMID 39400540, 2024).
cancer (continued). "Our result showed increased expression of ALKBH7 may have a protective effect on the development and progression of various cancers, particularly HNSC, by influencing metabolism and immune cell infiltration." (PMID 39400540, 2024). "In addition, correlation analysis of ALKBH7 with pan-cancer immune regulators showed that ALKBH7 expression was highly negatively correlated with the expression of chemokines, immune receptors, MHC, immunosuppressants, and immune activators." (PMID 39400540, 2024). "Therefore, it is imperative to conduct further mechanistic research to explore the role of ALKBH7 in cancer tumorigenesis and progression and to assess its value of potential as an anticancer therapeutic target." (PMID 39400540, 2024). "We found that DNA methylation could negatively affect ALKBH7 expression in multiple types of cancers." (PMID 39400540, 2024). "The results showed that ALKBH7 expression might be negatively correlated with all four methyltransferases in 6 types of cancers, including OV, PRAD, BRCA, COAD, DLBC, and KIRC." (PMID 39400540, 2024). "Studies have demonstrated that activation of ALKBH7 in apoptosis-resistant cancer cells may contribute to enhancing the toxic effects of chemotherapeutic alkylating agents in tumors, suggesting a potential alternative pathway for tumor eradication." (PMID 37654657, 2023). "Therefore, studying its substrates can clarify the role played by ALKBH7 in mitochondria and thus provide a deeper understanding of its regulatory role in cancer." (PMID 37007161, 2023). "Then, we investigated ALKBH7 expression in different cancer immune and molecular subtypes." (PMID 35222541, 2022). "In addition, the trends for the up- and downregulation of ALKBH7 expression were also different in different immune subtypes of a specific cancer type." (PMID 35222541, 2022). "Overall, this work provides evidence to elucidate the immunotherapeutic role of ALKBH7 in cancer, which may be helpful for further functional experiments." (PMID 35222541, 2022). "Our pan-cancer analysis provides insight into the role of ALKBH7 in different cancers." (PMID 35222541, 2022). "In addition, ALKBH7 expression was significantly correlated with the pathological stage of some cancers, including BLCA, KIRC and UCS." (PMID 35222541, 2022). "In addition, recent studies have identified a role for ALKBH7 in the progression of several cancers and its relationship with immune cell infiltration." (PMID 35222541, 2022). "However, more experimental studies are required to explore the specific mechanisms of ALKBH7 action in cancer." (PMID 35222541, 2022). "However, ALKBH7 expression correlates with clinical parameters (age, sex and pathological stage) in only a few patients with cancer." (PMID 35222541, 2022). "In conclusion, ALKBH7 may serve as a potential prognostic pan-cancer biomarker and is involved in the immune response." (PMID 35222541, 2022). "In addition, we performed an in-depth study of the immune mechanism of ALKBH7 in different cancers to explore its potential immunotherapeutic value." (PMID 35222541, 2022). "Moreover, ALKBH7 expression was associated and predominantly negatively correlated with the expression of immune checkpoint (ICP) genes in many cancers." (PMID 35222541, 2022). "Herein, several databases were employed at first to assess the different expression of ALKBH7 as well as their relationship to the prognosis, RNA modification, DNA methylation modulation, immune microenvironment and chemotherapeutic responses of various types of cancers." (PMID 39400540, 2024). "Therefore, a deep investigation of ALKBH7 in cancers is still required to verify whether it is an appropriate biomarker in prognosis of cancers." (PMID 39400540, 2024).
cancer (continued). "Based on Cell Miner and GDSC data, the analysis of IC50 values of different drugs in pan-cancer reveals that high ALKBH7 expression might be sensitive to most anti-cancer drugs, such as Palbociclib, Dovitinib, Vandetanib, Trametinib, Mirdametinib, and Pluripotin." (PMID 39400540, 2024). "The expression of ALKBH7 was also associated with the level of immune cell infiltration, TMB, MSI, HRD, MMR deficiency, and DNA methyltransferases in a wide variety of cancers, which might be potentially related to the responses against chemotherapeutic agents." (PMID 39400540, 2024). "However, how the ALKBH7 regulate the cancer progression and whether it is related to the prognosis of head and neck cancer has not been well understood yet." (PMID 39400540, 2024). "Notably, increased expression of ALKBH7 may have a protective effect on the development and progression of various cancers, particularly HNSC, by influencing metabolism and immune cell infiltration." (PMID 39400540, 2024). "Furthermore, a pan-cancer analysis showed that ALKBH7 expression correlates negatively with the expression of ICP genes in many types of cancer and that ALKBH7 gene co-expression networks regulate cellular immune, oxidative, phosphorylation, and metabolic pathways." (PMID 37007161, 2023). "Interestingly, ALKBH7 expression has some prognostic value for some cancers." (PMID 35222541, 2022). "Therefore, we hypothesized that ALKBH7, a potential pan-cancer biomarker or a novel immunotherapeutic target, may predict the response to immunotherapy or achieve promising therapeutic outcomes, respectively." (PMID 35222541, 2022). "In addition, ALKBH7 was related to mDNAsi in 12 cancers and mRNAsi in 13 cancers." (PMID 35222541, 2022). "While their study emphasized pan-cancer implications, ours reveals a subtype-specific role in BC, particularly in HER2+, highlighting ALKBH7’s relevance in immunometabolic regulation." (PMID 41373809, 2025). "To further validate the protective biofunction of ALKBH7 in pan cancer, especially in HNSC, we systematically analyzed the potential regulation effect of DNA methylation and RNA modification in ALKBH7 expression." (PMID 39400540, 2024). "The analysis against gene expression, its DNA methylation as well as RNA modification of ALKBH7 and its relationship to the prognosis and the tumor microenvironment such as TMB, MSI, HRD, and MMR of cancers was performed at first." (PMID 39400540, 2024). "Overall, we found that ALKBH7, MYCBP, MZF1, RRS1, and TUSC2 were reported to be involved in the development and progression of cancer." (PMID 37654657, 2023). "Altogether, ALKBH7, MYCBP, MZF1, RRS1, and TUSC2 were reported to be involved in the development and progression of cancer, and dysregulation of these genes was known to be highly correlated with tumorigenesis." (PMID 37654657, 2023). "Our study found that ALKBH7 was related to the immune, stromal, and ESTIMATE scores and immune cell infiltration in the TME of most human cancer types, especially in PAAD, PRAD and THCA." (PMID 35222541, 2022). "AlkB homolog 7 (ALKBH7) modulates alkylation-induced cellular death through a tissue- and sex-specific mechanism and has the potential to influence cancer cells." (PMID 36213507, 2022). "ALKBH7 expression showed a negative correlation with DNAss and DMPss, and a positive correlation with RNAss across various cancers in pan-cancer analysis." (PMID 39400540, 2024). "Except for ACC, HNSC, and KICH, ALKBH7 expression was significantly negatively correlated with the expression of five MMR genes in pan-cancer, which is also negatively correlated with all methyl transporter enzymes in multiple cancer types." (PMID 39400540, 2024). "The relationship between ALKBH7 expression and DSS in patients with cancer was examined." (PMID 35222541, 2022).
cancer (continued). "Although ALKBH7 expression did not correlate relatively significantly with the clinical parameters of age (6/33), sex (3/33) and stage (3/27) in the cancers studied, the results of the survival analysis reflect the pan-cancer prognostic value of ALKBH7." (PMID 35222541, 2022). "In addition, ALKBH7 expression was significantly correlated with the TMB (7/33), MSI (13/33), mDNAsi (12/33) and mRNAsi (13/33) in human cancers." (PMID 35222541, 2022). "Additionally, ALKBH7 expression displayed a positive correlation with MSI in 8 different cancer types such as DLBC, HNSC, and KIRC, but a negative correlation with MSI in READ, COAD, and LGG." (PMID 39400540, 2024). "The AlkB homolog 7 (ALKBH7) is a nonheme iron (II) α-ketoglutarate-dependent dioxygenase superfamily member, which may affect the progression of several types of human cancer." (PMID 39400540, 2024). "However, the prognostic value and immunological role of ALKBH7 in cancer have not been systematically investigated." (PMID 35222541, 2022). "However, the prognostic and immunotherapeutic value of ALKBH7 in different cancers have not been explored." (PMID 35222541, 2022).